BACH1 (BACH transcriptional regulator 1)
Diseases named in the same sentence as BACH1 in open-access papers (continued):
Sharing a sentence is not in itself a finding about the gene and the disease.
cancer (continued). "Considering that BACH1 promotes cancer progression, the negative regulatory role of TBK1 on BACH1 found in the present study may be modulated in cancer cells to a positive regulatory role, promoting BACH1 protein accumulation." (PMID 38673728, 2024). "Moreover, while BACH1 correlated positively with EMT and PD-L1 but negatively with oxidative phosphorylation and fatty acid oxidation, RKIP showed opposite trends in a pan-cancer manner." (PMID 37963558, 2023). "The relevance of BACH1 as a target could explain some of the CDDO-Me and CDDO-TFEA observed therapeutic benefits and provides a rationale for their novel use in other pathologies such as cancer metastasis." (PMID 35313207, 2022). "In addition to such a gate-keeper function of oxidative stress response, those studies discussed in this review have established that BACH1 (i.e., its presence) further increases, directly and indirectly via the GRN, the expression of genes critical for cancer progression (a“two-faced BACH1 model”)." (PMID 34339740, 2021). "Therefore, the BACH1 GRN may be a critical mechanism involved in the dynamic transition of EMT and MET in cancer cells." (PMID 34339740, 2021). "BACH1 may bring both EMT and ferroptosis sensitivity to metastatic cancer cells." (PMID 34339740, 2021). "Furthermore, recent reports have highlighted the potential value of BACH1 as a therapeutic target in cancer, and thus our study also opens the door for new lines of investigation focused on the potential value of CBD as a cancer therapeutic drug." (PMID 31518892, 2020). "Therefore, we hypothesized that by blocking Bach1 protein degradation through tyrosine kinase inhibition we could reverse DHA-induced HO-1 expression and more effectively suppress cancer cell viability." (PMID 30367621, 2018). "Therefore, depleting BACH1 using either shRNA or a non-toxic inhibitor hemin could elicit the lactate dependency of cancer cells, increase the efficacy of MCT1 inhibitors, and suggest better therapeutic options for those with TNBC." (PMID 35406740, 2022). "In addition, BACH1 may impose negative effects on the cancer cell survival by affecting protein homeostasis." (PMID 34339740, 2021). "Consistent with MAFF knockdown, we observed that inhibition of BACH1, IL11, or STAT3 did not change primary tumor growth, suggesting that their main role in cancer was not the regulation of cell proliferation in our experimental settings." (PMID 34262028, 2021). "Due to the role of BACH1 promoting cancer cell invasion and the lack of redundancy with NRF2, we hypothesised that BACH1 inhibitors would reduce cancer cell invasion, while NRF2 activators would not." (PMID 35313207, 2022). "After finding a negative correlation between RKIP and BACH1 in 31 different cancer types, they established the concept of a back-and-forth battle played out between an anti-metastatic ‘group’ led by RKIP and a pro-metastatic, such as EMT-inducing, led by BACH1." (PMID 39335152, 2024).
tumor (83 papers, 2006 to 2025). "In detail, SDCBP overexpression caused the accumulation of BACH1 and increased expressions of BACH1-regulated pro-metastatic genes, ultimately driving tumor progression in TNBC cells." (PMID 40263598, 2025). "Upregulated genes were associated with the meiotic cell cycle (PDIK1L) and tumor proliferation (BACH1 and PDIK1L)." (PMID 41333405, 2025). "We found positive associations between BACH1 expression and tumor size, tumor grade, and the basal-like subtype." (PMID 40710214, 2025). "BACH1 has been identified as a central regulator of these tumor-associated genes related to the promotion of metastasis." (PMID 38321558, 2024). "Overexpression of IGF1R and PTK2 rescued the inhibition of tumor growth and metastasis caused by BACH1-depletion." (PMID 35154476, 2022). "The elevated levels of BACH1 were related to increased tumor number, larger tumor size, tumor encapsulation loss, microvascular invasion, less differentiation, and poor tumor-nodule-metastasis (TNM) staging." (PMID 35154476, 2022). "The density of CD31+ blood vessels and the expression of vascular endothelial growth factor C (VEGFC) in tumor xenografts were significantly associated with BACH1 levels according to the results of IHC and immunofluorescence (IF) analyses performed in vivo." (PMID 33932125, 2021). "An increase in CD34+ tumor-associated blood vessel density was apparent in diaphragm specimens derived from mice injected with BACH1-overexpressing cells, as compared with control ES2 cells." (PMID 32132179, 2020). "Morphometric analyses indicate a significant increase in the relative area fraction occupied by LYVE1+ tumor-associated lymphatic vessels in diaphragm specimens removed from mice injected with BACH1-overexpressing ES2 cells." (PMID 32132179, 2020). "High level of miR-155-5p, which can target Bach1 mRNA, in the tumor tissue of CRC is associated with increased lymph node metastasis." (PMID 27999449, 2016). "Additionally, loss of SDCBP downregulated the transcriptions of BACH1-targeted pro-metastatic genes, thereby suppressing tumor progression in TNBC cells." (PMID 40263598, 2025). "In addition, in silico analyses of many tumor types suggest that BACH1 has a significant association with immune checkpoints and the tumor immune environment." (PMID 38321558, 2024). "However, BACH1 is negatively associated with NK T cells, and it is worth investigating if it suppresses the NK-mediated killing of tumor cells." (PMID 38321558, 2024). "Notably, the mechanisms underlying the roles of BACH1 in ferroptosis, oxidative stress and tumor microenvironment remain to be explored." (PMID 38321558, 2024). "Loss of Bach1 was able to repress tumor-sphere formation and tumor-initiating CSC markers." (PMID 34949193, 2021). "C (P < 0.05), tumor volume and weight were both decreased with the loss of Bach1 in vivo." (PMID 34949193, 2021). "Finally, one TF, BACH1, was found to be significantly upregulated in C1 subtypes; the pathways activated by this TF may be associated with tumor progression and poor prognoses." (PMID 35801241, 2022). "Knocking down SDCBP induces BACH1 degradation and downregulates expressions of BACH1-induced metastatic genes, thereby suppressing tumor progression in mice bearing TNBC tumors." (PMID 40263598, 2025). "We found that tumors from Black women had significantly higher BACH1 expression levels compared to those from White women when tumor grades were used as a controlled variable (p = 0.0399)." (PMID 40710214, 2025). "BACH1 expression levels were also different between the Grade 3 tumor group and the ND group (p = 0.009), with higher expression levels in the Grade 3 group compared to the ND group, which is an unclassified group." (PMID 40710214, 2025).
tumor (continued). "Higher tumor grade (grade 3) correlated with the highest levels of BACH1 and MCT1 in our patient cohort." (PMID 40710214, 2025). "Repression of BACH1 suppresses the spread of TNBC cells to the lungs and enhances their responsiveness to metformin, indicating that specifically blocking BACH1 can alter tumor metabolism by boosting mitochondrial metabolism." (PMID 39887888, 2025). "Accordingly, BACH1 depletion impairs tumour spread in preclinical models of lung, breast, and pancreatic cancer among others." (PMID 40716152, 2025). "Based on the post hoc pairwise comparisons, BACH1 expression levels were significantly higher in the Grade 1 tumor group than the Grade 3 group (p = 0.0488)." (PMID 40710214, 2025). "BACH1 has been characterized as an oxygen- and redox-sensitive transcription factor that governs tumor angiogenesis and vascular patterning, rendering tumors susceptible to anti-angiogenic therapies." (PMID 40312332, 2025). "An expression correlation analysis indicated that BACH1 IHC scores were positively correlated with tumor size." (PMID 40710214, 2025). "We also analyzed BACH1 IHC scores by tumor tissue type, and our data showed similar levels of BACH1 for the following tumor tissue types: DCIS, LCIS, hyperplasia, lymph node metastasis (LN-MTS), and tumors (T)." (PMID 40710214, 2025). "In the current study, we observed that BACH1 expression levels are positively correlated with tumor size and are significantly higher in histological Grade 3 tumors." (PMID 40710214, 2025). "WES analysis of 60 pRCC specimens revealed six tumours (10%) with mutations in the four key genes, NFE2L2, KEAP1, CUL3 and BACH1, of the NRF2‐ARE pathway." (PMID 39707614, 2025). "BACH1 promotes tumor cell proliferation and metastasis by altering tumor metabolism and the epithelial‐mesenchymal transition phenotype." (PMID 39887888, 2025). "Taken together, our data showed that BACH1 protein expression levels were relatively abundant in the Grade 3 tumor group, which was defined as poorly differentiated or dedifferentiated in our patient cohort." (PMID 40710214, 2025). "Past studies have shown that BACH1 promotes tumor progression in multiple ways and is a promising prognostic biomarker." (PMID 38321558, 2024). "Metformin was able to inhibit the growth of tumor cells and decrease tumor cell viability in BACH1-depleted TNBC cells." (PMID 38255314, 2024). "BACH1 facilitates tumor invasion and metastasis by regulating the EMT, ECM remodeling, and pro-metastatic factors." (PMID 38321558, 2024). "In order to further understand the immunomodulatory role of BACH1 in various tumors, we deeply analyzed the correlation between BACH1 and various tumor-infiltrating immune cells using the TIMER 2.0 database." (PMID 38321558, 2024). "The expression of BACH1 is markedly correlated with the pathological stage, tumor-node-metastasis (TNM) stage, distant metastasis, and survival outcomes." (PMID 38321558, 2024). "Fluorescence imaging of the lungs, following implantation of MDA-MB-231 WT or BACH1−/− tumor cells, revealed distinct metastatic patterns in response to dietary shifts." (PMID 38838145, 2024). "To that end, we generated MDA-MB-231 wild type (WT) or BACH1−/− cells using the Crispr method, injected them into athymic nude mice via tail vein, and studied the impact of different diets on tumor metastasis." (PMID 38838145, 2024). "By contrast, upon genetic knockout or pharmacological inhibition of endogenous BACH1, the Keto diet–mediated activation of those targets is largely diminished, and the effects on tumor metastasis are completely abolished." (PMID 38838145, 2024). "Given that BACH1 promotes ferroptosis, it is worth exploring the possibility of targeting BACH1 to facilitate ferroptosis in the tumor microenvironment." (PMID 38321558, 2024). "BACH1, for example, is highly expressed in tumours and is involved in epigenetic silencing during tumour progression." (PMID 38501838, 2024).
tumor (continued). "Next, we explored the in vivo effects of the Keto diet on BACH1/ATF4 function in an MDA-MB-231 xenograft tumor model." (PMID 38838145, 2024). "Clarifying the implication of divergent effects contributes to our understanding of the roles of BACH1 in the tumor immune microenvironment." (PMID 38321558, 2024). "BACH1 is widely expressed in dendritic cells, neutrophils, monocytes, and macrophages that are abundant in the tumor microenvironment (TME)." (PMID 38321558, 2024). "Together, these data implicate a distinct transcription regulatory program of BACH1 for tumor metastasis induced by the Keto diet." (PMID 38838145, 2024). "After dichotomizing tumor size (small: 3-25 in diameter vs. big: 27-85 mm in diameter), BACH1 expression scores were significantly higher (p = 0.015) in the bigger tumor group (mean [SD]; 4.20 [1.796]) compared with the smaller tumor group (3.920 [1.693])." (PMID 37461502, 2023). "The organism is a complex regulatory process, and proteins or transcription factors such as ErbB2 and BACH1, which are involved in tumor development, also have positive/negative regulation on HK II." (PMID 38202657, 2023). "KEAP1 eviction and NRF2 activation provoke tumor progression and metastasis in lung adenocarcinoma through the activation of BTB and CNC homology 1 (BACH1), which has been implicated in RAS-driven tumor formation." (PMID 37381723, 2023). "GADD45B-high tumor cells showed strong associations with transcription factors such as ELK1, PAX5, SMAD3, BACH1, and NR1H2." (PMID 37608794, 2023). "The tumor cells in both the BACH1-OE and siSCD1 groups showed more oxidized lipids (green fluorescence) than those in the control group, while OA addition significantly attenuated the oxidative phenotype." (PMID 36670112, 2023). "Antioxidants increased tumor vascularity in vivo in a BACH1-dependent fashion, and overexpressing BACH1 rendered tumors sensitive to antiangiogenesis therapy." (PMID 37651203, 2023). "The outcome of BACH1 stabilization following antioxidant administration — i.e., glycolysis and tumor progression — is like that of HIF1α, which is stabilized following hypoxia." (PMID 37651203, 2023). "Collectively, these findings suggest that lncRNA AC016727.1 promotes tumor proliferation, aggressive migration, and aerobic glycolytic progression via BACH1." (PMID 37946265, 2023). "This study identifies BACH1 as an oxygen- and redox-sensitive transcription factor that controls tumor angiogenesis and vascularity and renders tumors sensitive to antiangiogenic therapy." (PMID 37651203, 2023). "NAC and VitC administration increased tumor vascularity, and knockout of BACH1 abolished this effect." (PMID 37651203, 2023). "The master regulator of mitochondrial biogenesis, PPARG, as well as PPARGC1A and the downstream effectors and transcription factors NRF1 and BACH1, are upregulated in various metastases as compared to the primary tumor or to the target site." (PMID 38039408, 2023). "BACH1 expression is dynamically altered and likely to be epigenetically modified in colorectal malignant transformation and tumor progression." (PMID 37228820, 2023). "Nevertheless, knockdown of BACH1 dramatically abolished the increased tumor growth in the liver, the occurrence of pulmonary metastasis, and the number of pulmonary metastasis lesions, leading to prolonged OS." (PMID 35154476, 2022). "Our data analysis also showed the correlation of BACH1 with tumor infiltrated immune cells, including lymphoid cells and myeloid cells, for example, CD8+/4 + T cells, B cells, neutrophils, macrophages, and so on." (PMID 35651942, 2022). "We found that targeting lactate catabolic pathways, including MCT1, is more effective for tumor suppression when BACH1 levels are low." (PMID 35406740, 2022). "Overall, the results derived from human datasets and clinical samples strongly supported the possibility that UBR7 act as a tumor suppressor in HCC by regulating Keap1/Nrf2/Bach1/HK2 axis." (PMID 36419136, 2022).
tumor (continued). "Since BACH1 is a heme-binding transcription factor for cellular heme homeostasis, heme (hemin) was used as a tool to reduce BACH1 protein levels in numerous tumor models." (PMID 35406740, 2022). "BACH1 mRNA is highly expressed in subsets of monocytes, macrophages, neutrophils, and dendritic cells, which are abundant in the tumor microenvironment (TME)." (PMID 35035660, 2022). "The analysis showed that the expression in both negative vs. both positive groups (coexpression) of MALAT1 and BACH1 was correlated with the size of tumor, metastasis in LN, and TNM stage (p ≤ 0.000, 0.000, and 0.001, respectively)." (PMID 35096427, 2022). "Aiming to reveal the relationship between BACH1 expression and prognosis of tumor patients, the patients were divided into high-expression groups and low-expression groups based on the BACH1 expression level." (PMID 35651942, 2022). "BACH1’s expression in Liver hepatocellular carcinoma (LIHC) tumor tissue is positively correlated with all six kinds of immune cells." (PMID 35651942, 2022). "In orthotopic xenograft models, we found that BACH1 overexpression augmented tumor growth and BACH1 silencing alleviated tumor growth in the liver." (PMID 35154476, 2022). "The results of correlation of marker expression with clinicopathological characteristic of the studied TNBC showed that MALAT1 and BACH1 expression (positivity) is correlated with size of the tumor, nodal metastasis, and TNM stage (p < 0.001)." (PMID 35096427, 2022). "BTB domain and CNC homology 1 (BACH1) is a transcription factor that is highly expressed in tumors including breast and lung, relative to their non-tumor tissues." (PMID 33809182, 2021). "True as it is, pretreatment of NAC stabilized BACH1 in resistant MCL cells, and this finding is supported by recent studies demonstrating the tumor-promoting signature of stabilized BACH1 in human solid tumors." (PMID 34039348, 2021). "The nuclear BACH1 expression is associated with adverse clinical features in DLBCL, whereas BACH2 has been well-recognized as a tumor suppressor in many hematological malignancies." (PMID 34039348, 2021). "Here, we demonstrate that MAFF, which is induced by HIF-1 under hypoxia, binds with BACH1 and promotes tumor invasion and metastasis by transcriptionally activating IL11 and promoting STAT3 pathways." (PMID 34262028, 2021). "Knocking down BACH1 or both MAFF and BACH1 decreased tumor cell invasion and tube formation of HUVEC cells." (PMID 34262028, 2021). "In our study, cells with BACH1 knockdown indicate that BACH1 is responsible for tumor invasion and angiogenesis through an IL11-STAT3 pathway." (PMID 34262028, 2021). "BACH1 inhibits RasG12V-induced cellular senescence and enhances the tumor growth activity of primary mouse embryonic fibroblasts." (PMID 34339740, 2021). "In further studies, metformin treatment suppressed tumor growth from the mice xenografted using shBACH1 cells relative to the BACH1-enriched control tumors." (PMID 33809182, 2021). "Overall, these results suggested that BACH1 enhanced tumor growth in a xenograft model partially by facilitating angiogenesis and the EMT." (PMID 33932125, 2021). "Recent studies provide significant insights into NRF2 and BACH1 in tumor progression, including angiogenesis, tumor metabolism, endothelial-to-mesenchymal transition (EMT), and metastasis, suggesting possible links between small MAFs and tumor progression." (PMID 34262028, 2021). "Previous studies demonstrated that BTB and CNC homology 1 (BACH1) participates in various types of tumor metastasis." (PMID 33932125, 2021). "Emerging evidence point to BACH1, a ubiquitously expressed protein, as a tumor-promoting factor that acts via multiple intracellular signaling cascades." (PMID 32132179, 2020).